CCL5 (C-C motif chemokine ligand 5)
Diseases named in the same sentence as CCL5 in open-access papers (continued):
Sharing a sentence is not in itself a finding about the gene and the disease.
tumor (continued). "Other studies also showed that transfection of tumor cells with CCL5 can induce T cells to infiltrate tumor." (PMID 37660142, 2023). "Our data showed that CCL5 carryed by AdKi67-C3 or AdKi67-CCL5 did induce more CAR-T cells infiltrating into tumor mass in tumor-burden mice." (PMID 37660142, 2023). "It had been reported that tumor cells downregulate CCL5 expression through DNA methylation and chemokine circuitries to restrict T-cell infiltrating in tumors." (PMID 37660142, 2023). "Restricting the CCL5/CCR5 axis-mounted anti-tumor response lowers TAM trafficking and reduces tumor growth." (PMID 38035101, 2023). "CCL5 is a major metastasis-promoting inflammatory chemokine and is known to drive pro-oncogenic tumor–stroma interactions." (PMID 37444610, 2023). "In malignant melanoma, targeted inhibition of HIF-1α induced high levels of CCL2 and CCL5 expression and then increased the invasion of tumor-killing NK cells, CD3+, CD4+, and CD8+ T cells in tumor tissues." (PMID 36675491, 2023). "We further demonstrated that these effects are attributed, at least in part, to the increased expression of CXCL16 and CCL5 by MEPs, which in turn support the anti-tumor activity of CD8 + T cells and NK cells." (PMID 36646904, 2023). "IL-27 stimulates multiple lineages of immune cells, and IL-27-induced C–C motif ligand 5 (CCL5) contributes to IL-27 mediated anti-tumor activity." (PMID 37805495, 2023). "CCL5 is elevated in tumor-conditioned lymphatic endothelial cells and directs the dissemination of tumor cells into lungs and lymph nodes, promoting angiogenesis and colonization in distant organs." (PMID 36980201, 2023). "CCL5, VCAM1, and TLR2 have been demonstrated to be associated with the tumor immune microenvironment and promote PCa cell metastasis." (PMID 37494663, 2023). "The CCL5/CCR5 axis promotes tumor progression through a spectrum of mechanisms, such as enhancing invasion and metastasis of tumors, reducing tumor cell resistance to drugs, and recruiting immune and stromal cells." (PMID 36675305, 2023). "Macrophage-derived CCL5 has been found to promote immune escape from cancer, and its co-blockade with PD-L1 enhances the anti-tumor immune response." (PMID 36635779, 2023). "Clinically approved PARPis have been shown to induce IFN-I and CCL5 expression in tumor cells trough cGAS-STING." (PMID 36831435, 2023). "Gonadotroph tumor cells polarize macrophages to the M2 phenotype, while somatotroph and gonadotroph tumor cells can recruit macrophages via CCL5 and colony-stimulating factor-1 (CSF-1)." (PMID 37958702, 2023). "Taken together, these findings suggest that following gemcitabine therapy, MEPs directly affect CD8 + T cells and NK cells probably via the secretion of CXCL16 and CCL5, thereby contributing to anti-tumor immunity." (PMID 36646904, 2023). "High expression of CCL5 significantly suppresses the development of tumor cells, but its ability to increase the ratio of M2/M1 macrophages promotes the progression of cancer." (PMID 37529035, 2023). "A previous report has shown that intratumor NK cells recruited conventional type I dendritic cells (cDC1) to the tumor site via the production of CCL5." (PMID 38258042, 2023). "Previous studies have shown that CCL5 secreted from tumor cells results in increased infiltration of Tregs in multiple cancers." (PMID 37291128, 2023). "By secreting TGF-β, CCL2, CCL5, IL-6 etc., CAFs recruit immunosuppressive cells into the tumor stroma, which contributes to cancer metastasis and progression." (PMID 36843593, 2023). "Previous humanized mouse studies indicated that intratumoral injection of CAdVEC induced expression of chemokines CXCL10 and CCL5 at tumor sites." (PMID 36989357, 2023). "In the murine ER+ BC model, the use of an anti‐CCL5 neutralizing antibody significantly decreases the infiltration of macrophages and tumor volume." (PMID 36794651, 2023).
tumor (continued). "LMP1 can promote the expression of CCL5 and CCL2 in NPC cells, both of which can recruit tumour‐associated macrophages." (PMID 36519208, 2023). "Further analysis of the CCL5/Sp1/CD44 axis in EpCAM+ cells revealed that this signaling pathway was more activated in advanced tumor stages, which was consistent with the protein analysis." (PMID 37553567, 2023). "CD40 activation leads to an increase in CCL5 expression by TAMs allowing the recruitment of CD4+ T cells into the tumor, which are essential for tumor regression." (PMID 37143666, 2023). "As such, intratumor delivery of CCL5 mRNA with LNPs was shown to significantly reduce tumor growth, and IL-27 was found to induce robust CCL5 production by T cells resulting in antitumor activity." (PMID 37805495, 2023). "In this context, interleukins (ILs)-5, -7, -8, -9, -13 and chemokine C–C motif ligands (CCL)-5, -17, -20, -22, recruit inflammatory cells involved in tumor growth and immune escape." (PMID 37345141, 2023). "Further studies found that CCL5 enhanced autophagy in tumor cells and increased the migration ability of CRC cells by activating the AMPK signaling pathway, promoting the progression of CRC." (PMID 37141250, 2023). "CCL5 derived from tumor cells and C—X—C motif chemokine ligand 9 (CXCL9) secreted by IFN‐γ‐stimulated macrophages and DCs were critical for CD8+ T‐cell recruitment." (PMID 36599655, 2023). "Pro-tumorigenic chemo/cytokines such as IL-6, IL-10, CCL2, and CCL5 were decreased in NLRC5+ tumor-bearing ascites, correlating with significantly decreased frequency of tolerogenic DC2s subsets in this compartment." (PMID 38235131, 2023). "DC recruitment into the tumor, and differentiation are also mediated through NK cells, which produce cDC1 chemo-attractants CCL5, CXCL1, and survival stimulating cytokine FLT3LG." (PMID 37377970, 2023). "Emerging preclinical data show that targeting the autophagy-related gene Beclin-1 inhibits tumor growth and induces the infiltration of functional NK cells into the microenvironment of melanoma tumors in a CCL5-dependent manner." (PMID 37443821, 2023). "The inflammatory cytokines including IL-1β, IL-6, IL-8, and CCL-5 that are induced by NF-kB promote tumor growth through the induction of cell proliferation." (PMID 37340387, 2023). "This suppressive relationship RKIP has towards CCL5, one of the more potent pro-tumor chemokines, makes RKIP a prime target for silencing by the tumor in its advancement towards metastatic disease." (PMID 36765912, 2023). "CCL5 was found to be remarkably elevated in tumor tissues collected from PTC patients coexistent with HT than those without HT, and CXCL9, CXCL10, CXCL11, and CXCL13 were also reportedly upregulated in thyroid tissues from HT patients." (PMID 38137348, 2023). "CCL5 secreted by TAMs inhibits T cells and promotes tumor cell immune escape by stabilizing PD-L1 in vitro and in vivo." (PMID 37141250, 2023). "Cancer-associated immune cells are recruited in the tumor niche in response to several chemokines and cytokines released from tumor cells, such as CCL2, IL-8, CXCL12, and CCL5." (PMID 37592292, 2023). "In this study, the authors show that LECs residing in the lymph nodes and lungs are conditioned by tumor-secreted IL-6 to express and secrete CCL5 in a p-STAT3-HIF-1α-VEGF-dependent manner, creating an inflammatory PMN for metastasizing cells." (PMID 37887354, 2023). "IL-6 can also be produced by the tumor cells and secreted to interact with the IL-6 receptor on lymphatic endothelial cells (LECs) inducing production of the chemokine CCL-5." (PMID 36768435, 2023). "The potent lymphocyte attractor ligand CCL5 is reported to be prospectively upregulated in tumor-infiltrating CD4 + t cells following an initial immune stimulation to maintain t cell infiltration." (PMID 36906603, 2023). "The chemokine C-C motif ligand 5 (CCL5) is an inflammatory chemokine that promotes chemotaxis of immune cells to the tumor once an immune response is activated." (PMID 37754534, 2023).
tumor (continued). "Rantes (CCL5), which can induce anti-tumor immunity and cooperate with Th1 cytokines, such as IL-2 and IFN-γ, was found to be decreased after EV treatment on CD8 + T-cells." (PMID 37884996, 2023). "Taken together, these data indicated that tumor cell-autocrine adenosine upregulates CCL5 secretion through the Adora2a–p38–STAT1 pathway." (PMID 37291128, 2023). "TAMs release CCL5 to inhibit T cell-mediated killing of tumor cells and promote immune escape by stabilizing PD-L1 both in vitro and in vivo." (PMID 37936694, 2023). "Further, CXCL9 was positively related to CCL4, CCL5, CXCL10, and CXCL11 in UCEC, which are associated with DC, NK, and T cell recruitment and play an essential role in suppressing tumor growth and improving prognosis." (PMID 36845675, 2023). "Macrophages are recruited and educated by multiple factors in the TME, including colony-stimulating factor-1 (CSF1), GM-CSF, TGF-β, IL-1, IL-4, CCL2, CCL5, immune complexes, complement, histamine, tumor-derived non-coding RNAs." (PMID 38008741, 2023). "Analysis of clinical information and tumor sections from 48 PAAD patients showed that macrophage-derived CCL5 promotes the acquisition of cancer stemness, which is involved in GR." (PMID 37553567, 2023). "CCL5 inhibits tumor growth by promoting the infiltration of antitumor immune cells cDC1s into the TME, producing a more effective antitumor immune response." (PMID 37141250, 2023). "We compared the expression of the tumor-promoting chemokine CCL5 and its cognate receptors in these co-spheroids to indirect and direct standard 2D co-cultures." (PMID 37444610, 2023). "CCL5 is up-regulated in melanoma by autophagic inhibition, and it can promote tumor infiltration and antitumor immunity of NK cells." (PMID 35002511, 2022). "Whereas, Batf3 DCs can be recruited to the tumor bed through the chemokine (C-C motif) ligand 5 (CCL5) and XCL1 (also known as ATAC, lymphotactin, or SCM-1) produced by NK cells." (PMID 35626062, 2022). "The chemokines CCL-2 and CCL-5 attract macrophages into the tumor and lead to tumor progression and metastasis." (PMID 36611932, 2022). "M-MDSCs are recruited to tumors via a CCL1, CCL5-induced chemokine cascade that is disseminated by tumor cells, and CCL3 produced by TAMs is retained in the primary tumor." (PMID 36686745, 2022). "Similar research from Ma’s group suggests targeting bone marrow CCL5/CCR5 signaling via nanoparticle delivery is promising in modulating immature myeloid cells in their tumor model." (PMID 36361830, 2022). "On the other hand, CCL5 is a chemokine that appears to induce the activation of NK cells and enhances anti-tumor immunity in a mouse model." (PMID 36142615, 2022). "Chemokines such as CC chemokine ligand 2 (CCL2), CCL5, and vascular endothelial growth factor can recruit TAMs to the tumor-site, thus contributing to the maintenance of an immunosuppressive TME." (PMID 35740542, 2022). "It produces a series of chemokines and cytokines that regulate immunity, including IFN-γ, TNF, IL-6, and CCL5, which have the function of regulating immune response and anti-tumor and are related to the improvement of the overall survival rate of patients." (PMID 36686745, 2022). "CCL5 has been progressively investigated in tumor immunotherapy in recent years with some achievements." (PMID 36387070, 2022). "This study aimed to identify the fibroblast-mediated effect of tumor bud-derived C–C chemokine ligand 5 (CCL5) on the tumor microenvironment (TME)." (PMID 35241150, 2022). "Within the tumor, cancer cells secrete CCL5 and sustain the proliferation of CCR5-positive cells, recruit T-regulatory cells and monocytes, cause osteoclast activation and bone metastasis, neo-angiogenesis and cancer cells dissemination." (PMID 36430633, 2022). "The data revealed that CCL5 is expressed in HCC tumor tissues and its expression is significantly correlated with NLRC3 (P<0.0001, R2 = 0.2372)." (PMID 35145917, 2022).
tumor (continued). "PGE2 also prevents NK cells from secreting XCL1 and CCL5, highlighting its function as an immunosuppressive mediator to prevent cDC1s from migrating to the tumor." (PMID 36703982, 2022). "Regarding HCC, a catenin beta 1 (CTNNB1)-activating mutation is frequently observed and reported to flourish in an immune-desert tumor microenvironment, partly via C-C motif chemokine ligand 5 (CCL5) downregulation." (PMID 35884434, 2022). "In contrast, tumor-infiltrating NK cells have induced cDC1s recruitment by CCL5 and XCL1 production, and promote cDC development and proliferation, with FMS-like tyrosine kinase 3 ligand (FLT3L)." (PMID 35784290, 2022). "Tumor associated macrophages influence tumor progression through secretion of cytokines such as IL-10, INF-γ and CCL5." (PMID 36338755, 2022). "The CCL5/RANTES chemokine is well-known as an important contributor for tumor invasion and metastasis." (PMID 35327361, 2022). "Several studies have shown that a high level of CCL5 induces tumor cell proliferation, migration and angiogenesis." (PMID 35327361, 2022). "The role for CCR5 has been documented in T-cell recruitment to the tumor site, and local production of CCL5 or CCL3 induces selective recruitment of CD8 T cells and CTL-dependent tumor suppression in mouse models." (PMID 35530341, 2022). "There are numerous findings on the role of CCL5 in CRC development, with some reports suggesting that CCL5 inhibits tumor growth, while others suggesting that CCL5 promotes CRC development." (PMID 36387070, 2022). "Studies have shown that the high expression of CCL5 in CRC tumor cells can promote their proliferation." (PMID 35241150, 2022). "CCL5 is recognised by a range of chemokine receptors that are maintained on ex vivo stimulated T cells such as CCR1, CCR3, and CCR5, making CCL5 a good candidate for tumour-specific expression to target adoptively transferred lymphocyte migration." (PMID 35205725, 2022). "A recently studied, reported that CCL5 was involved in tumour recurrence through macrophage accumulation in residual tumours, which was in turn responsible for collagen deposition." (PMID 35406451, 2022). "Among the differentially expressed proteins, CCL5 showed the most up-regulation in CM samples from human CRC tumor cells." (PMID 35241150, 2022). "At the invasive front, CCL5 was highly expressed in tumor buds, which were surrounded by a high number of α-SMAhigh CD90high FAPlow fibroblasts and blood vessels." (PMID 35241150, 2022). "The CIBERSORT method was used to further confirm the relationship between CCL5 expression and immune components, construct immune cell profiles and analyze the proportion of tumor infiltrating immune subtypes." (PMID 35252266, 2022). "CCL2 and CCL5 are responsible for the recruitment of macrophages into the tumor microenvironment and tumor development." (PMID 35677043, 2022). "CCL2 had the highest serum level in naïve mice, followed by CCL4 and CCL5, and their concentrations increased from the early to late stage of metastasis, just like in mice with the s.c. tumours." (PMID 36241867, 2022). "A small amount of CCL5 produced by tumor cells is released outside the cell and binds to the corresponding receptor." (PMID 36033472, 2022). "Myeloid-derived suppressor cells (MDSCs) are also present in TME in high amounts, contributing to tumor invasion and growth, while they are regulated by many tumor-derived substances, such as CCL5, as well as CCL2." (PMID 35743107, 2022). "In summary, we demonstrated the prognostic significance of macrophages and aPKCɩ in CCA, and then identified the Macrophages-aPKCɩ-CCL5 positive feedback loop in the tumor microenvironment that accelerates CCA progression and chemoresistance." (PMID 35033156, 2022). "Tumor cells regulate antitumor immune responses by secreting CCL5, which attracts Treg cells to the tumor microenvironment and enhances their ability to kill CD8+ T cells." (PMID 36387070, 2022).
tumor (continued). "Recently, it has been found that the infiltration level of CD8+ T cells in OC is regulated by CXCL9 expressed in antigen presentation cells (APCs) and CCL5 expressed in tumor cells." (PMID 36532066, 2022). "Chemokine CCL5 participates in the proliferation and migration of tumor cells, as well as angiogenesis and lymphangiogenesis, by binding to receptors CCR5, CCR3 and CCR1." (PMID 36514094, 2022). "By the time the CCL5-dependent collagen VI surrounds the tumor, it is likely there are already metastases." (PMID 36430633, 2022). "A co-culture recruitment assay showed that the ability of tumor cells to recruit fibroblasts was significantly weakened after CCL5 knockdown." (PMID 35241150, 2022). "CCL5 is regularly epigenetically silenced in tumor cells but can be reactivated by decitabine (DNA methyltransferase inhibitor)." (PMID 36387070, 2022). "Another chemokine, CCL5 expressed by tumor cells not only induces macrophage recruitment, but also promotes the secretion of more EVs by tumor cells, whereby EVs educated macrophages into TAMs and enhanced metastasis in the lung." (PMID 36430471, 2022). "Western blot analyses on 4 paired fresh tumor and normal samples also exhibited significantly increased CCL5 expression in 6 paired tumor tissues compared with para-tumor kidney tissues." (PMID 35982911, 2022). "CCL5 recruits the TAMs which possess the pro-tumor properties to suppress the anti-tumor immune response and produce vascular endothelial growth factor (VEGF), fibroblast growth factor (FGF) to promote angiogenesis, epithelial-to-mesenchymal transition." (PMID 35083488, 2022). "Studies have shown that CCL5 directly affects the transport of immune cells and participates in anti-tumor immune response." (PMID 35710862, 2022). "Tumor-associated macrophages (TAMs) have been reported to be associated consisting of highly expressed CCL2, CCL3, CCL5, CCL18, CXCL1, and CXCL12 in the TME." (PMID 35935996, 2022). "In a murine model, XCL1 and CCL5 were mainly produced by NK cells and attracted conventional type 1 dendritic cells (cDC1) into the tumor microenvironment." (PMID 35626062, 2022). "CC-motif chemokine ligand 5 (CCL5) belongs to an important CC subfamily of chemotactic cytokines that can be secreted either by tumor cells or by stromal cells." (PMID 35701840, 2022). "We also assessed the ability of tumor-associated neutrophils to possibly recruit other immune system cells, and evaluated the release of CCL2/MCP-1 and CCL5/RANTES by neutrophils stimulated with MDA-EVs." (PMID 35741003, 2022). "CCL5, a significant member of chemotactic cytokines, plays an important role in CAFs promoting tumor development." (PMID 35589690, 2022). "Mechanically, CCL5−/− mildly decreases the percentage of MDSCs, increases DC maturation and macrophage’s inflammatory function at an early stage after tumor inoculation, and later up-regulate the level of Th1 and down-regulate the level of Tregs." (PMID 35327361, 2022). "The combination of both anti-CCL5 and anti-PD-L1 inhibited tumour growth, in both a cFOXP3 Pan02 xenograft model and an orthotopic murine model, via the stimulation of cytotoxic T cells." (PMID 35626020, 2022). "CDC1 is recruited through the CCL5/CCR5 axis to infiltrate into tumor tissue and then exert anti-tumor effects." (PMID 36387070, 2022). "Elevated CCL5 can recruit macrophages to tumour tissues and promote their polarization to the immunosuppressive M2 subtype, thereby facilitating metastasis." (PMID 35365161, 2022). "HRS cells, by secreting CCL5, can recruit HL-MSCs, which in turn can recruit monocytes and protect tumor cells against drug activity." (PMID 35626032, 2022). "The DEN/CCl4-treated Cxcl10−/− mice, in turn, displayed a significant enhancement of chemokines in tumor tissue in comparison to the surrounding tissue (Ccl5, Ccl2 and Ccl7)." (PMID 35897689, 2022).